CD4 (CD4 molecule)
Diseases named in the same sentence as CD4 in open-access papers (continued):
Sharing a sentence is not in itself a finding about the gene and the disease.
AIDS (continued). "It has been notably shown that persons living with HIV-2 progress to AIDS with higher CD4+ T-cell counts than persons living with HIV-163." (PMID 36813761, 2023). "Others, although infected but without antiretroviral therapy, control HIV-1 replication and progression to AIDS; they are named controllers, maintaining low viral levels and an adequate count of CD4+ T lymphocytes." (PMID 37457832, 2023). "Estimation of CD4 depletion model parameters using the national HIV/AIDS surveillance system database (HASS) in male and female patients." (PMID 37139388, 2023). "The frequency of productively infected cells tended to be higher during AIDS in comparison with recent and long-term infections (median, 340, 72, and 32/million CD4+ T cells, respectively) and correlated with the plasma viral load at all stages of infection." (PMID 38420260, 2023). "Several studies have shown that CD4+ T cell count and albumin levels are the two main markers that can be considered the first indices to look at in terms of AIDS progression." (PMID 37736888, 2023). "In Singapore, the late presenter rate between 2012 and 2017 was estimated at 45% (CD4 count <200 cells/mm3 at the time of diagnosis or an AIDS-defining illness at diagnosis or within one year of HIV diagnosis)." (PMID 37351535, 2023). "Among the estimated 2,400 people in Germany with an initial HIV diagnosis in 2021, the Robert Koch Institute (RKI) estimates that 790 people (33%) were diagnosed with advanced immunodeficiency (AIDS or CD4 cell count of less than 200)." (PMID 37626414, 2023). "The median CD4+ T-cell counts were 365, 313, 43, and 553/mm3 during recent, long-term infections, AIDS, and under ART, respectively." (PMID 38420260, 2023). "Late presentation, or accessing care with a CD4 cell-count <350 cells/μL or with an AIDS-defining illness, has several consequences on an individual clinical, public health, and health systems level." (PMID 36753495, 2023). "The manufacturer of the LAg-Avidity assay recommends excluding individuals who are receiving ART or elite suppressors or have AIDS (CD4 cell count < 200 cells/μL) from incidence surveys." (PMID 37766353, 2023). "Logistic regression was used to assess factors associated with the risk of AIDS at diagnosis ([AIDSAD], defined as a CD4 count < 200 cells/μL) in patients with HIV subtype B, CRF01_AE, and CRF07_BC." (PMID 35260599, 2022). "In a number of countries, including Poland, as many as 45–60% of patients are diagnosed with HIV/AIDS very late and at the stage of full-blown AIDS, usually with severe immunodeficiency and a CD4 T-lymphocyte count below 350 cells/mm3 (late presenters)." (PMID 36011138, 2022). "The CD4+ T cells/CD8+ T cells ratio (CD4/CD8 ratio) has shown an association with both AIDS and non-AIDS events in virologically suppressed individuals." (PMID 35428209, 2022). "Martins proposed a joint model with flexible links using standard deviation of residuals as a predictor to assess the stability of CD4 counts on survival outcome in patients with HIV/AIDS." (PMID 35869438, 2022). "Patients were stratified according to lower or greater likelihood of immune activation (CD4 nadir < 200, previous AIDS-defining event or very-low-level viremia during follow-up)." (PMID 35632669, 2022). "Further, CD8 T cells from AIDS patients demonstrated lower anti-viral activity when co-cultured with autologous, naturally infected CD4 cells or with acutely infected CD4 cells." (PMID 36172358, 2022). "Patients diagnosed with AIDS also showed a statistically significant increase in CD4+ T-cell counts." (PMID 35713430, 2022). "The mean baseline CD4 was 516.4 cells/uL, with a viral load (VL) of 4.49 log10, and 11.4% were in the AIDS stage." (PMID 35336931, 2022). "An analysis of the simian immunodeficiency virus (SIV) reported that the progression to AIDS results in a decreased CD4 cell count and increased viremia, as well as the transfer of intestinal microbiota into the bloodstream." (PMID 35632692, 2022).
AIDS (continued). "In HIV infections, a higher concentration of suPAR was observed in patients with a lower number of CD4+ lymphocytes, a higher viral load and greater AIDS-related mortality." (PMID 35330458, 2022). "We present a rare case of PbL in a 55-year-old male with HIV-AIDS (CD4 (cluster of differentiation 4) cell count of 128), who presented for evaluation of incidentally detected multiple liver masses and lytic lesions in the ribs." (PMID 36726933, 2022). "A slower CD4+ T cell depletion and progression to AIDS and an increase in natural HIV-1 control with lower HIV-1 viral load has been reported in HTLV-2/HIV-1 coinfected patients in the absence of antiretroviral treatment." (PMID 36366570, 2022). "Current evidence suggests that highly active antiretroviral therapy (HAART) can significantly reduce viral replication in HIV/AIDS patients, increase the CD4+ T lymphocyte count and reconstruct the immune function of patients." (PMID 36195585, 2022). "A total of 35,515 patients were included, of whom 63.0% were male; 64.7% at the age group of 30 to 49 years, 64.4% were white, 12.9% co-infected with TB, and 37.6% had CD4 count above 200 cells/mm3 at diagnosis of AIDS." (PMID 35246066, 2022). "This resulting inversed CD4/CD8 ratio has been associated with frailty and premature ageing of the immune system leading to higher non-AIDS-related morbidity and mortality rates." (PMID 36846557, 2022). "Predictors of late presentation (defined as CD4 ≤350 or AIDS-defining illness within 3 months of diagnosis) and prolonged interval between diagnosis and ART initiation were assessed by multivariable regressions." (PMID 36103496, 2022). "Other studies in Brazil found that SU was correlated with lower CD4-cell counts, another measure of TF, and shorter time to progression to AIDS." (PMID 35742448, 2022). "In a literature study of 342 cases of aspergillosis in AIDS patients, CD4 counts were reported in 140 cases; and in 133 (95%) cases, the CD4 count was <100 cells/mm3." (PMID 36354898, 2022). "Having < 200 CD4 cells/μl was a significant independent predictor of intestinal microsporidiosis among HIV/AIDS patients in the present study, increasing the likelihood of infection by threefold." (PMID 34983416, 2022). "Secondly, the selection of treatment plan for naïve HIV/AIDS patients needs comprehensive evaluation of various factors, including age, co-infection, CD4+T cell counts, viral load and drug side effects." (PMID 35308227, 2022). "From 2008 to 2009, the indicator for free ART initiation was CD4+T-cell count of <200 cells/mm3 or advanced AIDS status." (PMID 36568791, 2022). "The univariate analysis showed that, apart from seasonality and AIDS stages, CD4+ counts were significant predictors (p < 0.05)." (PMID 36067140, 2022). "Exacerbates viral rebound after ART interruption.Accelerates the reactivation of the latent reservoir and AIDS progression.Increased CD4 and CD8 T cell counts.Improve SIV-specific CD4+ and CD8+ T cell immune function." (PMID 35336991, 2022). "For 37 of the 67 patients in this review, the diagnosis of AIDS was made based on the report of CD4+ count < 200 cells/mm3." (PMID 35305282, 2022). "Antiretroviral treatment can assist in the prevention of AIDS but monitoring CD4+ T cell count and viral load through testing and point-of-care services can help in disease management." (PMID 36354458, 2022). "This indicates a need for greater clinical suspicion of aspergillosis in HIV/AIDS patients at all stages, but particularly in those with CD4 counts <100 cells/mm3 to initiate prompt, sometimes life-saving treatment." (PMID 36354898, 2022). "The most significant clinical challenges in people living with HIV/AIDS (PLWHA) are decline in CD4+ T helper cells and abnormal weight reduction." (PMID 35029192, 2022).
AIDS (continued). "Although long-term antiretroviral therapy (ART) prompts CD4 T-cell recovery, some immune defects persist such as immune activation, low CD4/CD8 ratio and risk of developing inflammatory non-AIDS comorbidity." (PMID 35098197, 2022). "The most significant clinical challenges in people living with HIV/AIDS (PLWHA) are decline in CD4+ T helper cells and abnormal reduction in weight." (PMID 35029192, 2022). "The AIDS patients with CD4+ T cell count less than 350 cells/μl should be given antiretroviral therapy or other treatments according to the World Health Organization (WHO)." (PMID 36312587, 2022). "The World Health Organization (WHO) has emphasized the use of CD4 counting in assessing early disease status, monitoring AIDS progression, making clinical decisions, and prioritizing care for advanced HIV patients." (PMID 35846073, 2022). "Test of significant difference after 6 weeks’ comparative effects of progressive resistance exercise and moderate intensity aerobic exercise on CD4 counts of people living with HIV/AIDS." (PMID 35029192, 2022). "While depletion of CD4+ T cells and progression to AIDS occurs in both males and females, there are significant sex-related differences in the course of infection." (PMID 35693831, 2022). "At treatment initiation, 47.4% (n = 144) presented at WHO clinical stages I and II (early stages of infection) and 45.7% (n = 139) had CD4 count ≥ 200 cells/mm3 (non-AIDS stage)." (PMID 37448990, 2022). "Compared with HCs, no significant decrease in biventricular ejection fraction or volume was found in ART-treated males with AIDS with different levels of CD4+ T-cell counts (all p > 0.05)." (PMID 36292106, 2022). "Due to the lower number of CD4+ T cells, INR were at greater risk of poor long-term prognoses such as disease progression, opportunistic infections and AIDS-related mortality despite viral suppression after years of continuous HAART." (PMID 36411423, 2022). "The beneficial effects of selenium nutritional supplementation were reported in a few studies by a decrease in viral burden, an increase in the time of progression to AIDS and an indirect increase in the number of CD4 T cells." (PMID 35163318, 2022). "A strong predictor of the progression to Acquired Immunodeficiency Syndrome (AIDS) is the CD4+ T-cell (CD4) count typically reported as an absolute level or count of cells (expressed as cells per cubic millimeter of blood)." (PMID 34983418, 2022). "HIV replication induces the apoptosis of CD4 lymphocytes, leading to the development of acquired immunodeficiency syndrome (AIDS)." (PMID 35062355, 2022). "AIDS is defined as having a CD4 T cell count below 200 cells per liter of blood or presenting with an AIDS-defining illness." (PMID 35600204, 2022). "The number of MLWH presenting to Danish HIV care with a CD4+ T-cell count < 350 cells/μL or AIDS decreased from 44 (59%) in 1995–99 to 19 (13%) in 2015–20." (PMID 35904057, 2022). "This situation is more pronounced in persons who have progressed to AIDS, which, in Canada, is defined as having a CD4+ cell count of < 200 cells per cubic millimeter (cells/mm3) and/or the presence of AIDS‐related opportunistic infections." (PMID 35305282, 2022). "For this, pooled SE or SP derived from 50 donors was titrated on TZM-bl cells, a HeLa cell derivative widely used in AIDS research that is engineered to express the HIV-1 receptors CD4 and CCR5." (PMID 35955696, 2022). "At each person’s initial visit, all study patients were treatment naïve, allowing for between-group comparisons of HIV-1 viral load, CD4 counts, opportunistic infections and AIDS-defining opportunistic infections." (PMID 36363801, 2022). "HIV-2 is characterized by a longer asymptomatic stage, a slower decline of CD4+ T cells, lower mortality related to AIDS (Acquired Immunodeficiency Syndrome), and lower person-to-person transmission rates than HIV-1." (PMID 35476802, 2022).
AIDS (continued). "In this study, the multivariable Cox proportional hazards regression model indicated that the five factors (Shingles, CD4, BMI, HB and TC) were associated with the HIV/AIDS-related survival time." (PMID 34991536, 2022). "While this test is currently not used in HIV detection, it can be implemented for point-of-care AIDS management by assessing blood levels of CD4+ cells for antiretroviral therapy." (PMID 36354458, 2022). "AIDS increases vulnerability to opportunistic infections due to low CD4+ T-helper (Th) cell counts, high viral load and immune dysfunction." (PMID 35203323, 2022). "The defect of intestinal structure and immune function leads to gut microbiota dysbiosis and microbial translocation, followed by systemic immune activation, ultimately accelerating the depletion of CD4+ T cells and the progression to AIDS." (PMID 36685491, 2022). "In Africa where M. tuberculosis is common in the community, HIV infection also enhances susceptibility even if this organism isn't readily classified as strictly “opportunistic” and is more common even at CD4 counts above those defining AIDS." (PMID 35775044, 2022). "Similar to HIV-1 infections, viruses with CXCR4 use have been isolated from HIV-2-infected individuals with low CD4+ T-cell counts or clinical symptoms of AIDS." (PMID 36366545, 2022). "ART-treated males with AIDS were divided into subgroups according to their CD4+ T-cell counts (<350 cells/μL and ≥350 cells/μL) and duration of disease (1–12 months, 13–24 months, and 25–36 months)." (PMID 36292106, 2022). "The chimpanzee developed several clinical hallmarks of AIDS (high viremia [105-106 SIVcpz copies/ml of plasma], massive CD4+ T-cell depletion [220 cells/ul], and thrombocytopenia [90,000 platelets/ul]), and was effectively treated with antiretroviral therapy." (PMID 36713371, 2022). "This study aimed to determine several common etiologies of FUO stratified by CD4 count levels in HIV/AIDS patients." (PMID 35042469, 2022). "A diagnosis of AIDS (based on the presence of opportunistic infections or a CD4 count lower than 200 cells/mm3) showed suggestive (but statistically insignificant) correlations, especially in the tri-task condition (p = 0.066)." (PMID 38235449, 2022). "This study implies that guidelines for appropriate testing to identify the etiology of FUO in HIV/AIDS patient based on the CD4 cell count should be developed, thereby reducing resource waste." (PMID 35042469, 2022). "Among LP, 27% initiated ART with a CD4 cell count <100 cells/μL, 21·8% with 100–199 cells/μL and 51·6% with 200–350 cells/μL, and 13·2% had an AIDS-defining event at baseline." (PMID 35958520, 2022). "Persistent immune activation, which occurs during the whole course of HIV infection, plays a pivotal role in CD4+ T cells depletion and AIDS progression." (PMID 35967422, 2022). "The nadir CD4+ T-cell count was 241 (91.2–405.5), and 17.8% of the patients had been diagnosed with AIDS." (PMID 35713430, 2022). "The only sample from which the majority of sequences were from viruses predicted to use CXCR4 (four of five sequences) was from an individual that developed AIDS (CD4+ T-cell count = 138 cells/μL, CD4% = 17) at the time-point when this sample was taken." (PMID 36366545, 2022). "In 2020, 179,000 cases (IQR 133,000–219,000) of cryptococcal disease were estimated in people with HIV and CD4 < 200 cells/μL, accounting for 19% (13–24%) of AIDS-related mortality." (PMID 36547617, 2022). "Treatment-naive viral load set point is associated with the rate of HIV disease progression, as measured by time to CD4 counts of <200/mm3, AIDS, and death." (PMID 35720328, 2022). "These cohort studies have consistently found subtype D to be more virulent than subtype A1, with faster drops in CD4 counts and more rapid progression to AIDS)." (PMID 36514107, 2022). "Oral candidiasis still remains a significant opportunistic infectious disease in advanced stages of AIDS with CD4+ T-cell counts <200 cells/μl." (PMID 35250957, 2022).
AIDS (continued). "In HIV/AIDS patients, due to immune suppression, particularly quantitative and qualitative CD4+ T cell defects, limited inflammatory responses are induced, which facilitates fungal growth in the CNS." (PMID 36557672, 2022). "Low CD4+ T-cell nadir has been shown to be a relevant to a worse prognostic for other HIV but also for other non-AIDS comorbidities." (PMID 35109939, 2022). "The Department of Health and Human Services (DHHS) defined that HIV/AIDS patients with CD4+ T cell count still below 350 or 500 cells/μl after 4-7 years of ART are considered to be INRs." (PMID 36325329, 2022). "CM has an important role in the treatment of HIV/AIDS in China, showing a good curative effect in ameliorating symptoms and signs, improving quality of life, increasing CD4+ T-cell counts, and prolonging survival in PLWHA." (PMID 35929632, 2022). "A large number of HIV/AIDS patients in the married group had a CD4 cell count < 200 cells/μl, while the majority that were unmarried, divorced, or widowed had ≥ 200 cells/μl." (PMID 35646738, 2022). "Shortly after the initiation of ART, there is a rapid increase in the peripheral CD4+ cell count and CD4+ cell count recovery with ART use is associated with a significant reduction in the risk of AIDS and non-AIDS diseases or death." (PMID 35324948, 2022). "Progressors are characterized by lower CD4+ T lymphocytes, higher viral load levels, and a rapid progression to AIDS, whereas LTNPs and ECs possess higher CD4+ T lymphocytes and lower viral load levels, which lead to better control of HIV-1 infection." (PMID 36499177, 2022). "The acute phase of HIV-1 infection is characterized by a significant decrease in CD4+ T lymphocyte counts that persisted throughout the chronic phase, resulting in the lymphopenia seen in untreated AIDS patients." (PMID 35335016, 2022). "Only a small proportion had advanced liver disease (4%) or a current AIDS related illness (4%) and 35% were asymptomatic with a current CD4 cell count > 500 cells/μl (CDC clinical staging—A1)." (PMID 35962372, 2022). "By this process, HIV replication leads to pathogenesis via the destruction of CD4+ T cells and the development of AIDS." (PMID 36007015, 2022). "People with baseline CD4 count <200 cells/mm3 and a history of AIDS diagnosis had a statistically significantly higher prevalence of hyperglycemia." (PMID 36301817, 2022). "AIDS is defined by the development of major OIs (and, in parallel, including HIV-associated dementia, HAD) or by a CD4+ count falling below 200 per μl." (PMID 35775044, 2022). "In addition, studies showed that HIV-1/HTLV-1 coinfected patients maintain stable CD4+ T-cell counts that may conceal the immunosuppression associated with the progression to AIDS, which may affect the clinical decision-making related to prophylaxis for opportunistic infections." (PMID 36363801, 2022). "Previous studies collectively suggested that a lower CD4/CD8 ratio during cART is associated with a persistently higher HIV DNA, AIDS- or non-AIDS-related events and deaths, and frailty of older HIV-infected adults." (PMID 35873145, 2022). "As defined by The European Late Presenter Consensus working group, patients with advanced HIV infection are those who CD4+ T-cell count < 200 cells/μL or with an AIDS-defining event." (PMID 36700216, 2022). "As an indicator of AIDS clinical characteristics, CD4+ T cell count reflects the number of immune cells in patients." (PMID 36312587, 2022). "R thus represented the reduction in CD4 counts, ΔCD4, relative to the reduction signifying AIDS, ΔCD4AIDS." (PMID 35271687, 2022). "The odds of a female HIV patient reporting to the health facility with CD4 count < 200 cells/mm3 (AIDS) at treatment initiation was lower (OR = 0.52; 95% CI = 0.31 – 0.90) when compared with their male counterparts." (PMID 37448990, 2022).